EPHA2 (EPH receptor A2)
Diseases named in the same sentence as EPHA2 in open-access papers (continued):
Sharing a sentence is not in itself a finding about the gene and the disease.
tumor (continued). "We found Ephrin B3, Ephrin A1 and EphA2 all to have higher expression in tumor tissue relative to surrounding non-tumorous tissue." (PMID 27533087, 2016). "Determination of the mechanism maintaining tumour stemness is one of the most important challenges in current oncology and might also involve collaboration of RSK and EphA2." (PMID 26158630, 2015). "There was, however, no direct anti-tumor effect delivered upon treatment of MLL-AF9 mice with EphA2 monoclonal antibody (IF7 mAb)." (PMID 26083390, 2015). "Taken together, these results indicate that the phosphorylation of EphA2 at Ser-897 is controlled by RSK and the RSK–EphA2 axis might contribute to cell motility and promote tumour malignant progression." (PMID 26158630, 2015). "EphA2 has been shown to have no expression in most normal tissues and is highly expressed in several tumor types." (PMID 26313909, 2015). "We identify a novel pathway that linking HIC1 downregulation to EphA2-inducing EMT in ESCC cells and may shed light on the development of novel anti-tumor therapeutics." (PMID 26510908, 2015). "The cross-talk between EphA2 and EGFR signalling supported evidence that simultaneously inhibiting both EphA2 and EGFR overexpression may provide better anti-tumor response." (PMID 24495444, 2014). "Thus we performed an immunohistochemical analysis demonstrating that overexpression of EphA2 and induction of EMT occurred in the tumor cells of this case." (PMID 24606764, 2014). "Tumor growth reduction was significant in the RDES EphA2-kd model (P≤0.05) and considerable (about 50%) although not reaching significance (P = 0.19) in the TC71 EphA2-kd model." (PMID 23951165, 2013). "It is important to note, however, that the often contrasting data reported on Erk, Akt, and FAK signaling by EphA2 are context dependent and no coherent picture has come up to date on the role of such complex network in Eph-dependent tumor progression." (PMID 20130824, 2009). "Immuno-staining revealed a high-level expression of EphA2 in the GL261 tumor; whereas the normal brain did not demonstrate significant staining." (PMID 17295916, 2007). "Interestingly, flow cytometric analysis on these lungs did not recapitulate results from the previous experiment, specifically no decrease in lymphocyte populations in EphA2-overexpressing tumor-bearing lungs." (PMID 40867322, 2025). "EphA2 CAR-T cells showed higher killing efficiency of A549 cells and increased secretion of IFN-γ, TNF-α and granzyme B. In contrast, studies in xenograft mouse models confirmed that A549 tumor growth was suppressed and the number of cells infiltrating the tumor had elevated." (PMID 40428391, 2025). "Moreover, the EphA2/focal adhesion kinase (FAK)/RhoA signaling pathway has been reported to play an important role in the malignant behavior (i.e., resistance to apoptosis, cell migration, invasion, and angiogenesis) of tumor cells." (PMID 41440001, 2025). "Anti-EphA2-CD11b-BsAb is a functional targeting molecule and would require optimization through molar activity or blocking with nonradiolabeled antibody to maximize tumor targeting." (PMID 40434019, 2025). "Furthermore, IVC suppresses the transcriptional activity of VE-cadherin, EphA2, MMP2/9/14, PI3K, and LAMC2, as well as the protein expression of VE-cadherin, EphA2, and MMP2/9, thereby blocking tumor cell adhesion, ECM degradation, and the maintenance of vascular-like structures in HCC." (PMID 41019994, 2025). "Due to the well-established correlation of both EphA2 and SASH1 with tumor onset and progression, herein, to investigate how/if the formation of the SASH1-Sam1/EphA2-Sam complex could affect EphA2 activities in cancer, we focused on cancer-linked mutations in SASH1-Sam1." (PMID 39942820, 2025).
tumor (continued). "From a therapeutic perspective, targeting the molecular components of the “Black” module, such as WNT5A, EPHA2, and EGFR, could offer promising strategies to counteract tumor invasiveness and overcome drug resistance, particularly in Cluster B patients, who may be more responsive to such inhibitors." (PMID 41465101, 2025). "While EphA2 was expressed in tumor tissue, it was not detectable in osteoblast cells." (PMID 39056783, 2024). "EPHA2 and EP300 mutations consistently show decreased dNdS ratios in the presence of ATM mutation contexts compared to those without ATM mutation contexts across three tumor types, respectively." (PMID 39160568, 2024). "Non-canonical EphA2 activation plays a key role in tumor progression; however, its activation mechanism remains unclear." (PMID 37059179, 2023). "Additionally, one study reported localisation of VE-cadherin and EphA2 to vessels, but did not confirm by IF that cells lining the vessel were tumour cells rather than endothelial cells." (PMID 36823554, 2023). "The most important point of the present results is that these pro-tumor functions may be regulated by stress-induced non-canonical EphA2 activation via the p38-MK2 pathway, possibly in cooperation with ERK-mediated EphA2 activation." (PMID 37059179, 2023). "Furthermore, the EphA2 inhibitor ALW-II-41-27 could effectively reduce EphA2 pS897 and tumor cell stemness in vitro and significantly enhance the sensitivity of xenografts to the chemotherapeutic drugs PTX and DDP in vivo." (PMID 37063424, 2023). "Unfortunately, the only clinical trial incorporating a patient with advanced NSCLC could not describe objective anti-tumor effects after anti-EPHA2 DS-8895a antibody administration, hence questioning the results of the preclinical studies." (PMID 36613532, 2022). "Thus, the tumor suppression was resulted from inhibitors and simultaneously targeting PDGFRA and EPHA2 could effectively repress GBM growth in vivo." (PMID 35105853, 2022). "Ephrin ligand mimicking peptides engineered into multivalent structures have been shown to be potent stimulators of canonical EphA2 activity, with subsequent internalisation and degradation of the receptor, preventing non-canonical EphA2 activity and thereby suppressing tumour progression." (PMID 35869144, 2022). "Hence, it seems that EPHA2 expression is not merely related to the cell of origin of the different tumor types (i.e., mesenchymal vs. epithelial)." (PMID 34831119, 2021). "To test our hypothesis that virus-based TAA expression would produce a tumor antigen-specific antitumor immune response that suppressed tumor growth and improve survival, we created and validated a series of oncolytic HSVs that express regions of the C57BL/6 EphA2 gene." (PMID 34599026, 2021). "Advanced PCa cells express high levels of Integrin α3, α6, and β1 (ITGA3/A6/B1), EphA2, and connexins (Cx) such as Cx43/45 at their surface, and also increase levels of extracellular matrix (ECM) components including fibronectin (FN), osteopontin (OPN), and hyaluronan in tumor stroma." (PMID 33413659, 2021). "One approach is to construct bispecific CAR-T cells to target EphA2-negative tumor cells." (PMID 34503279, 2021). "Therefore, it is speculated that EphA2 CAR-T cells mainly influence EWS growth and metastasis by acting on tumor angiogenesis, which hypothesis clearly requires further experiments to test." (PMID 34566963, 2021). "Notably, while EFNA1 depletion clearly reduced tumor-suppressive EphA2-pY588, as expected upon depletion of the ligand-mediated signaling, EFNA5 silencing left EphA2-pY588 essentially unaltered in OVCAR3 and even increased this tyrosine phosphorylated receptor in OVCAR4." (PMID 33893375, 2021).
tumor (continued). "More recently, the ability of an anti-EphA2 BiTE secreted by retrovirally transduced primary T cells demonstrated the ability of STAb-T cells to redirect the cytotoxic activity of non-transduced T cells specifically to EphA2+ cancer cells in vitro and showed potent anti-tumor activity in vivo." (PMID 32903593, 2020). "Consistently, this tumor‐suppressive EphA2 axis was most prevalent in the untreated cisplatin‐sensitive TYK‐nu, while the acute TYK‐nu.R sensitivity to LJH685 was coupled with increased EphA2‐pY588 (NA after collapsed cell viability by combinatorial treatment)." (PMID 32115889, 2020). "We used EphA2-positive (U373, LM7) and EphA2-negative (BV173) tumor cell lines as target cells." (PMID 33148882, 2020). "DS-8895a is a humanized anti-EPHA2 IgG1 monoclonal antibody that is afucosylated to enhance ADCC (POTELLIGENT®; BioWa Inc., Princeton, NJ, USA) and is expected to produce antitumor effects on EPHA2-overexpressing tumor cells through ADCC, as demonstrated in pre-clinical studies." (PMID 31412935, 2019). "Tumor shrinkage demonstrated no clear correlation with DS-8895a dose or EPHA2 expression." (PMID 31412935, 2019). "Given that heterodimers of EphA2 and EGFR do exist in tumor cells, one may speculate that by altering the EphA2 interactome Ephrin B3 may influence such EphA2/EGFR heterodimers and in this way control Akt Ser 129 and EphA2 Ser897, resulting in block of EphA2 mediated invasion/migration signaling." (PMID 27533087, 2016). "Additionally, FAK/RhoA signaling can act as downstream effectors of EphA2 for promoting tumor progression in non-metastatic RCC cells." (PMID 26177500, 2015). "Moreover, Hsp90 is an essential regulator of EphA2 stability and signaling, which is highly expressed in several cancer cells and is recognized by the host as a self-protein, thus limiting the ability of CD8+ T cells to recognize and kill the tumor." (PMID 26501335, 2015). "This might be explained by the pro-oncogenic function of EPHA2 in the absence of EFNA1, whereas activation of EPHA2 by EFNA1 promoted tumor suppression by triggering receptor degradation." (PMID 25025847, 2014). "One could speculate that tumor cells with an “aggressive” expression status, i.e. over-expression of EPHA1 and EPHA2 as well as down-regulation of EFNA1, possess a survival advantage under adverse conditions and thus, are capable of thriving in the foreign microenvironment of secondary sites." (PMID 25025847, 2014). "It is not clear whether EphA2 phosphorylation or its overexpression plays a role in tumor progression." (PMID 23951165, 2013). "However, the regulating factors and mechanisms by which ephrin-A1/EphA2 promote tumor angiogenesis were not well clarified." (PMID 24040255, 2013). "However, if receptor EphA2 activation with ephrin-A1 induced expression of cdx-2 plays any role in NSCLC tumor growth is not known." (PMID 22824143, 2012). "This may explain why 2/3 patients experienced pulmonary edema, which might have been a result of “on-target, off-tumor” toxicity as EphA2 is not usually expressed on normal tissue except on lung epithelium and preclinical studies had suggested this as a consequence." (PMID 37754534, 2023). "However, the researchers also observed that treatment with EphA2-targeted CAR T cells may lead to an increase in EphA2-negative tumor cells, which could potentially result in tumor immune escape." (PMID 36983330, 2023). "Finally, the combination of EphA2 ADCs with immunotherapies such as PD-L1 inhibitors and agonists of the glucocorticoid induced TNF receptor-related protein (GITR) in the CT26 model resulted in dramatic anti-tumour responses once again lending credence to potential for effective synergy." (PMID 36046842, 2022).
tumor (continued). "Based on our results, we concluded that EphA2, EphA3, EphA4, and EphA5 were down-regulated in BCs, and high expression levels of these genes indicated better RFS, suggesting that EphA2, EphA3, EphA4, and EphA5 act as tumor suppressors in BC and could be new biomarkers for its prognosis." (PMID 34221956, 2021). "Furthermore, pharmacological inhibition of EphA2 through the small molecule inhibitor ALW-II-41-27 reduced the proliferation of sunitinib-resistant tumor cells, suppressed tumor growth in vivo, and restored the sensitivity of sunitinib-resistant tumor cells to sunitinib in vitro and in vivo." (PMID 32814829, 2020). "However, the unique ligand-dependent tumor suppressor functions may make development of EphA2 agonists, rather than antagonists, a fruitful strategy for targeted therapy of a variety of solid tumors." (PMID 22916121, 2012). "EPHA2 confers tumorigenic and metastatic potential to non-transformed breast and skin epithelial cells, as well as mouse fibroblasts, and is overexpressed in tumor parenchyma of several cancers, including breast, bladder, prostate, colon, eosophageal, ovarian, cervical, stomach, and melanoma." (PMID 20979646, 2010). "We suggest that through the inhibition of ligand-induced EphA2 degradation, dasatinib might act to stabilise receptor/ligand binding, thereby promoting adhesive rather than repulsive interactions, and suppressing tumour invasiveness." (PMID 18797457, 2008). "To test the impact of tumor-specific EphA2, we overexpressed EphA2 in murine NSCLC cells and found higher tumor burden in syngeneic but not in immunocompromised mice." (PMID 40867322, 2025). "EphA2-silenced and non-silenced canine OS cells were injected subcutaneously in the flank region of NOD–SCID mice (1.0 × 106 cells per animal), and tumor formation was monitored." (PMID 39056783, 2024). "Mice treated with MOG SynNotch-EphA2/IL13Ra2 CAR T cells again showed superior tumor control and survival with no killing detected outside of the tumor in normal brain tissue." (PMID 37754534, 2023). "EphA2-4B3, a mAb specific to human EphA2, was [64Cu]-labeled through conjugation to the chelator NOTA and effectively delineated tumor boundaries in three different GB mouse models." (PMID 34209513, 2021). "In comparison to constitutively active anti-EGFRvIII/EphA2/IL13Rα2 CAR T cells, synNotch-CAR T cells showed greater anti-tumor efficacy without off-tumor toxicity." (PMID 34298615, 2021). "Although PBMC with CD19/CD3 BiTE did not exhibit cytolytic activity in CD19-negative tumor cell lines (U251, RERF, and A549), PBMC with EphA2/CD3 BiTE was cytotoxic to these cells expressing EphA2, particularly EphA2 high-expressing U251 cells." (PMID 30796310, 2019). "Although the mechanistic basis of its tumor-promoting function is not well defined, eHsp90 dependent AKT activation is required for EphA2 invasive action within defined models." (PMID 29290990, 2017). "CD19-ENG T cells secreted IFNγ after coculture with CD19-positive tumor cells (BV173, Daudi, Raji) while EphA2-ENG T cells did not (p < 0.001)." (PMID 27255991, 2016). "In tumor xenograft studies in nude mice, MEDI-547 inhibited the growth of EphA2-expressing tumors with no obvious adverse effects." (PMID 22370972, 2013). "Interestingly, we showed increased abundance of EPHA2 and much more massive increase of PGFRB in tumours compared with non-tumorous (histologically normal) tissue, consistent with our previous pilot study." (PMID 36890818, 2023). "EphA2-TEA-OVV, which expresses a bispecific T cell engager targeting CD3, EphA2, or EpCAM, exhibits notable anti-tumor activity and bystander killing of non-infected tumor cells." (PMID 37615308, 2023). "However, there has been no study involving the regulation relationship of EPHA2 and DUSP1 in any tumor." (PMID 37057290, 2023). "Similarly, gene expression of EPHA2, KDR, LAMC2, MMP1, and MMP14 did not vary between tumours of mice treated without and with aspirin." (PMID 32246008, 2020).
tumor (continued). "Additionally, both forward and reverse IP experiments revealed no detectable interactions between EphA2 and EFNA2 or EFNA5, suggesting that other receptors and downstream pathways may mediate the tumor-suppressive roles of EFNA2 and EFNA5." (PMID 39964764, 2025). "The in vivo specificity of BCY18469 towards EphA2 was proven by both PET imaging in an EphA2-negative cell line (MCF-7) and blocking with an excess on non-radiolabeled BCY18469, with both experiments showing no significant uptake and no tumor-to-background contrast." (PMID 39239524, 2024). "Similarly, EphA2-TEA-VV directed T-cells towards cancer cells, activated T-cells through secretion of IFN-γ, IL-2, and binding to CD3, and induced bystander killing of noninfected tumor cells." (PMID 38558795, 2024). "However, EphA2 has its limits, including an increase in EphA2-negative tumor cells after treatment with EphA2-targeted CAR-T cells, which may lead to tumor immune escape." (PMID 34503279, 2021). "The use of EphA2-ECD-Fc has been shown to reduce tumour angiogenesis in vivo in Rip1Tag2 pancreatic and 4T1 breast tumour models; it also had inhibitory effects on bovine microvascular cells in vitro but not on the 4T1 tumour cells in culture demonstrating vasculature specific effects." (PMID 26620208, 2016).